MARK1 (microtubule affinity regulating kinase 1)
Description:
Serine/threonine-protein kinase. Involved in cell polarity and microtubule dynamics regulation. Phosphorylates DCX, MAP2 and MAP4. Phosphorylates the microtubule-associated protein MAPT/TAU. Involved in cell polarity by phosphorylating the microtubule-associated proteins MAP2, MAP4 and MAPT/TAU at KXGS motifs, causing detachment from microtubules, and their disassembly. Involved in the regulation of neuronal migration through its dual activities in regulating cellular polarity and microtubule dynamics, possibly by phosphorylating and regulating DCX. Also acts as a positive regulator of the Wnt signaling pathway, probably by mediating phosphorylation of dishevelled proteins (DVL1, DVL2 and/or DVL3).
Synonyms: Par-1c; Par1c; MARK
Tractability: Small molecule: a high-quality ligand is known; it has a high-quality binding pocket; it belongs to a druggable protein family. Antibody: UniProt places it where antibodies can reach, with high confidence; its Gene Ontology location is reachable by antibodies, with high confidence. PROTAC: ubiquitination databases record sites on it; its protein half-life has been measured; a small molecule that binds it is known.
Target class: Protein Kinase; Kinase; CAMK protein kinase group; CAMK protein kinase MARK subfamily; CAMK protein kinase CAMK1 family; Enzyme
Gene: Protein-coding gene on chromosome 1 (220,528,086 to 220,664,461, forward strand). Ensembl gene ENSG00000116141.
Subcellular location: Cell membrane; Cytoplasm, cytoskeleton; Cytoplasm; Cell projection, dendrite
Gene Ontology:
Molecular function: ATP binding; magnesium ion binding; phosphatidic acid binding; phosphatidylinositol-4,5-bisphosphate binding; phosphatidylserine binding; protein binding; protein serine kinase activity; protein serine/threonine kinase activity; tau-protein kinase activity; tau protein binding; protein kinase activity
Biological process: intracellular signal transduction; negative regulation of epithelial to mesenchymal transition; negative regulation of gene expression; positive regulation of gene expression; protein phosphorylation; cytoskeleton organization; establishment of mitochondrion localization; microtubule cytoskeleton organization; neuron migration; regulation of dendrite development; regulation of neuron projection development; regulation of postsynapse assembly
Cellular component: cytoplasm; dendrite; plasma membrane; cytoskeleton; microtubule cytoskeleton; glutamatergic synapse; postsynapse
Genetic constraint (gnomAD): Loss-of-function variants: 23 observed, 56.5 expected, observed/expected ratio (o/e) 0.41, 90% interval 0.29 to 0.58. The upper end of that interval is the gene's LOEUF score, 0.58, which puts it in group 2 of 6, group 1 being the genes least tolerant of losing a copy. Missense variants: 529 observed, 736.59 expected, observed/expected ratio (o/e) 0.72, 90% interval 0.67 to 0.77. Synonymous variants: 232 observed, 269.82 expected, observed/expected ratio (o/e) 0.86, 90% interval 0.77 to 0.96.
Homologues: Orthologues: chimpanzee MARK1 (99% identical), macaque MARK1 (99% identical), rabbit MARK1 (98% identical), dog MARK1 (98% identical), pig MARK1 (96% identical), guinea pig MARK1 (94% identical), mouse Mark1 (94% identical), rat Mark1 (94% identical), tropical clawed frog mark1 (88% identical). Paralogues in human: MARK3 (70% identical), MARK2 (64% identical), MARK4 (55% identical).
Diseases named in the same sentence as MARK1 in open-access papers:
MARK1 is named in the same sentence as 67 diseases in open-access papers, as found by Europe PMC text mining. Sharing a sentence is not in itself a finding about the gene and the disease. The quoted sentences say what the papers report.
breast carcinoma (8 papers, 2018 to 2024). "In Basal-like breast cancer, both MARK1 and MARK3 were positively associated with patient survival in the pre-chemotherapy group but negatively associated with survival post-chemotherapy." (PMID 34084284, 2021). "In all breast cancer combined, high expression of LKB1, AMPK, LYK5, MARK1, MARK2, NUAK2, PAK1 (both probe sets), SIK1, SIK2, BRSK1, BRSK2, SNRK, and QSK was positively correlated with improved survival compared to low expression of these genes." (PMID 34084284, 2021).
Alzheimer disease (7 papers, 2008 to 2025). A progressive, neurodegenerative disease characterized by loss of function and death of nerve cells in several areas of the brain leading to loss of cognitive function such as memory and language. "MARK1 has been shown to regulate microtubule assembly, neuronal differentiation and tau toxicity an event implicated in late-onset Alzheimer’s disease." (PMID 23469157, 2013). "More recently, the MARK1-tau axis has been shown to play a critical role in mediating the toxic effects of Aβ on synapses and dendritic spines, neurodegenerative processes broadly associated with Alzheimer’s disease." (PMID 23469157, 2013).
autism (4 papers, 2012 to 2025). Persistent deficits in social interaction and communication and interaction as well as a markedly restricted repertoire of activity and interest as well as repetitive patterns of behavior. "For example, a ~35 Mb region on the chromosome at the loci 1q41-q42.2 which has been linked to autism and covers five SNPs significantly associated with autism in the MARK1 gene which showed an elevated dN/dS ratio indicative of adaptive evolution." (PMID 27414027, 2016). "Consistent with this, increased mRNA levels of MARK1 have been found in post mortem frontal cortex samples from autism subjects." (PMID 23083465, 2012).
liver cancer (4 papers, 2020 to 2024). An epithelial or non-epithelial malignant neoplasm that arises from the liver. "This study is just a preliminary study on part of the mechanism of MARK1’s negative regulation of POTEE on liver cancer cells." (PMID 39534429, 2024). "For example, MARK1 is amplified in various cancer types, such as breast and liver cancer, and MARK2 is upregulated in lung cancer." (PMID 35017636, 2022). "In contrast with its role as an oncogene in glioma and osteosarcoma, miR-1908 may act as a tumor suppressor in liver cancer by targeting MARK1 (Microtubule affinity-regulating kinase 1) signaling pathway." (PMID 32650755, 2020).
cervical cancer (3 papers, 2021 to 2024). A primary or metastatic malignant neoplasm involving the cervix. "Emerging studies indicated that circular RNA hsa_circ_ 0023404 and its target miR-217/MARK1 axis play a critical role in cancer progression such as non-small cell lung cancer and cervical cancer." (PMID 36352482, 2022). "These indicated that hsa_circ_0023404 and its target miR-217/MARK1 axis play a critical role in cancer progression such as non-small cell lung cancer and cervical cancer, but the role of hsa_circ_0023404/miR-217/MARK1 involved in endometrial cancer was not investigated yet." (PMID 36352482, 2022).
colorectal cancer (3 papers, 2021 to 2024). A primary or metastatic malignant neoplasm that affects the colon or rectum. "Recently, MARK1 has been discovered as the direct target of microRNA in both cervical and colorectal cancer where it was linked to proliferation and cell migration." (PMID 38784015, 2024).
hepatocellular carcinoma (3 papers, 2023 to 2024). A malignant tumor that arises from hepatocytes. "This study aimed to investigate the role of microtubule-affinity regulatory protein kinase 1 (MARK1) in hepatocellular carcinoma (HCC) progression, its association with sorafenib sensitivity, and the interplay between MARK1 and POTE Ankyrin domain family member E(POTEE) in HCC cells." (PMID 39534429, 2024).
colon cancer (2 papers, 2014 to 2021). "From the common edible plants 11 were found to have compounds targeting 3 proteins (MARK1, SMAD3, GSK3B) of the KEGG colon cancer pathway and 28 targeting the remaining 9, which are first-degree neighbors of the proteins in the KEGG colon cancer pathway." (PMID 24886433, 2014).
nasopharyngeal carcinoma (2 papers, 2017 to 2022). A carcinoma arising from the nasopharyngeal epithelium. "Previously, the overexpression of serum exosomal miR-106a-5p and miR-20a-5p was reported to enhance cell proliferation and differentiation by down-regulating the MARK1 signaling pathway in nasopharyngeal carcinoma (NPC)." (PMID 29156844, 2017). "In nasopharyngeal carcinoma (NPC), miR-1908-5p is overexpressed in TW03 (EBV-) cell exosomes, which can down-regulate the MARK1 signaling pathway, thereby promoting the proliferation and differentiation of NPC cells." (PMID 35463352, 2022).
prostate carcinoma (2 papers, 2013 to 2023). A carcinoma that arises from epithelial cells of the prostate gland. "Although no mutation or deletion of MARK1 has been reported in the tumors that were surveyed, the transcription levels of MARK1 showed significant upregulation in squamous lung cancer samples and during the progression of prostate cancer." (PMID 23940457, 2013).
atherosclerosis (1 paper, 2024). A disease characterized by the build-up of fatty material and calcium deposition in the arterial wall resulting in partial or complete occlusion of the arterial lumen. "MARK1, MARK3, and MARK4 have been reported to activate Hippo kinases, which may have implications for atherosclerosis development since activation of the Hippo kinase (mammalian STE20-like) MST1 has been reported to suppress EC activation when exposed to disturbed flow." (PMID 38892400, 2024).
autism spectrum disorder (1 paper, 2017). A spectrum of developmental disorders that includes autism, and Asperger syndrome. "MARK1 levels are elevated in Autism spectrum disorders (ASDs), a neurodevelopmental disorder." (PMID 28222093, 2017).
ciliopathy (1 paper, 2022). A genetic disorder of the cellular cilia or the cilia anchoring structures, the basal bodies, or of ciliary function. "Lastly, our meta-analyses also found marginal evidence for an association between severe COVID-19 and pLoFs (M1) in RILPL1 (OR: 20.2, 95% CI: 5.8–70.7, p = 2.42x10-6), a gene that, like MARK1, is associated with microtubule formation and ciliopathy." (PMID 36327219, 2022).
COVID-19 (1 paper, 2022). A disease caused by infection with severe acute respiratory syndrome coronavirus 2. "With ACAT, the association between TLR7 and severe COVID-19 (p = 1.58x10-6), and between MARK1 and hospitalisation (p = 4.30x10-7) remained exome-significant." (PMID 36327219, 2022). "In the meta-analyses, we also found that pLoFs (M1) in MARK1 were associated with a 23.9-fold increase in the odds of severe COVID-19 (95% CI: 6.5–88.2, p = 1.89x10-6), and a 12.3-fold increase in the odds of hospitalisation due to COVID-19 (95% CI: 4.8–31.2, p = 1.43x10-7)." (PMID 36327219, 2022). "Data for the M1 mask for TLR7 and MARK1 in the severe COVID-19 phenotype was then replicated with the GenOMICC cohort, a prospective study enrolling critically ill individuals with COVID-19, with controls selected from the 100,000 genomes cohort." (PMID 36327219, 2022). "Third, while the largest biobanks contributed the most to the signal observed at TLR7 and MARK1, many of our smaller prospective COVID-19 specific cohorts also contributed to the signal." (PMID 36327219, 2022). "MARK1 has previously been shown to interact with the SARS-CoV-2 ORF9b protein, further supporting its potential role in COVID-19." (PMID 36327219, 2022).
endometrial cancer (1 paper, 2022). Primary or metastatic malignant neoplasm involving the endometrium (mucous membrane that lines the endometrial cavity). "This study provided the strong evidence that hsa_circ_0023404 promoted the proliferation, migration and invasion in endometrial cancer cells through regulating miR-217/MARK1 axis." (PMID 36352482, 2022). "MARK1 is downstream target of miR217 and upregulated by hsa_circ_ 0023404/miR-217 axis and involved in the endometrial cancer progression." (PMID 36352482, 2022). "hsa_circ_0023404 exerts a tumor-promoting role in endometrial cancer by regulating miR-217/MARK1 axis." (PMID 36352482, 2022). "In this study, our data demonstrated that hsa_circ_0023404 exerts a tumor-promoting role in endometrial cancer by regulating miR-217/MARK1 axis." (PMID 36352482, 2022). "RT-qPCR showed that the levels of hsa_circ_0023404 and MARK1 mRNA were upregulated, but mirR-217 was decreased in three endometrial cancer cell lines." (PMID 36352482, 2022). "MARK1 is downstream target of miR217 and the induced MARK1 by hsa_circ_0023404 through miR217 inhibition contribute to the endometrial cancer progression." (PMID 36352482, 2022). "In further study, knockdown of MARK1 blocked the promotion of cancer biology mediated by si-circ_0023404/miR-217 axis, supporting that MARK1 is the target of miR-217 and involved in circ_0023404/miR-217-mediated endometrial cancer biology." (PMID 36352482, 2022). "However, the role of hsa_circ_0023404/miR-217/MARK1 involved in endometrial cancer (EC) was not investigated yet." (PMID 36352482, 2022).
influenza (1 paper, 2021). An acute viral infection of the respiratory tract, occurring in isolated cases, in epidemics, or in pandemics; it is caused by serologically different strains of viruses (influenzaviruses) designated A, B, and C, has a 3-day incubation period, and usually lasts for 3 to 10 days. "Using influenza as a model, live attenuated and killed inactivated influenza vaccines stimulate many shared pathways such as signaling of many interleukins (including IL-1, IL-4, IL-6, IL-13, IL-20, and IL-27), interferon signaling, MARK1 activation, and neutrophil degranulation." (PMID 33777032, 2021).
myelofibrosis (1 paper, 2022). A partial or complete replacement of the bone marrow stroma by fibrous tissue. "Interestingly, fedratinib, a selective oral JAK2 inhibitor recently approved in the United States for treatment of adult patients with myelofibrosis, which has off-target activity against the VIPs BRD4, TBK1, MARK1 and CSNK2A2, also displayed a similar proviral effect in our disease system." (PMID 36305426, 2022).
cancer (35 papers, 2012 to 2025). A tumor composed of atypical neoplastic, often pleomorphic cells that invade other tissues. "To further elucidate this question, we characterized the mutation and expression of MARK1 in different cancer samples using the COSMIC and GEO databases." (PMID 23940457, 2013). "Furthermore, MARK1 is a substrate of LKB1, a well-known tumor suppressor gene linked to metastatic outgrowth of cancer cells." (PMID 38784015, 2024). "Bioinformatics identified MARK1 protein is the target of miR‐217 in cancer cells." (PMID 36352482, 2022). "Therefore, LKB1 is the upstream regulator of AMPK and MARK1, and play a key role in cancer cell invasion and ECM remodeling and realignment." (PMID 28045069, 2017). "In this study, a large number of clinical samples of HCC patients for the first time were used to investigate the role of MARK1 and POTEE in the development of this cancer." (PMID 39534429, 2024). "It was demonstrated that MARK1 and MAPK14 can affect the multiplication and apoptosis in cancer cells." (PMID 36003525, 2022). "On the contrary, miR-486-5p was found to promote EC cell invasiveness by targeting Microtubule affinity regulating kinase 1 (MARK1), a tumor suppressor in several types of cancer." (PMID 34298609, 2021). "qPCR results showed that MARK1 expression in HCC cancer tissues and cell lines was decreased compared to that in para-carcinoma tissues and normal liver cell lines, while POTEE was increased to varying degrees, indicating that MARK1 and POTEE play an essential part in the progression of HCC." (PMID 39534429, 2024). "The results showed that inhibiting LKB1 or MARK1 in NSCLC increases the collagen fiber alignment and captures outward alignment vectors from the tumor spheroid, corresponding to high invasiveness of LKB1 mutant cancer cells." (PMID 28045069, 2017). "We found a reduction in MARK1 expression and an increase in POTEE expression in HCC tissues in comparison to the adjacent ones, suggesting that MARK1 may serve as a tumor suppressor gene in this cancer." (PMID 39534429, 2024).
tumor (29 papers, 2013 to 2025). "MARKs (MARK1-4) are members of the AMPK family and, like AMPK, can be activated downstream of the tumor suppressor LKB143,44." (PMID 34504101, 2021). "In principle, any one of these ARKs could exert tumour suppressor effects of LKB1, and indeed there is evidence that two of them, MARK1 and MARK4, are involved in the epithelial-to-mesenchymal transition, which is important in tumour metastasis." (PMID 33375416, 2020). "Vice versa, proliferation also occurred at the same level in the tumor cells Mark1/Melan A positive as in the negative (Ki-67 image)." (PMID 26378036, 2015). "Further, it has been reported that LKB1 loss-mediated epithelial-to-mesenchymal transition (EMT) occurs through the downstream kinases MARK1 and 4, not AMPK, suggesting an AMPK-independent signaling pathway that is essential for LKB1-dependent control of tumor aggressiveness." (PMID 35011738, 2022).
infection (2 papers, 2022 to 2024). The state of being infected such as from the introduction of a foreign agent such as serum, vaccine, antigenic substance or organism. "We previously identified MARK1, MARK2 and MARK3 kinases as interaction partners of Orf9b35 and ongoing studies will reveal their role in infection and the innate response." (PMID 34942634, 2022).
MARK1 also shares sentences with these, for which no sentence is quoted: melanoma (5 papers); lung carcinoma (4); neurodegenerative disease (4); tauopathy (4); glioma (3); Hyperinsulinemia (3); pancreatic cancer (3); Hyperglycemia (2); neurodevelopmental disorder (2); non-small cell lung carcinoma (2); squamous cell carcinoma (2); adenocarcinoma (1); amoebiasis (1); asthma (1); bladder (1); cervical tumor (1); chronic liver failure (1); colitis (1); Cushing syndrome (1); developmental delay (1); diabetic nephropathy (1); Down syndrome (1); endothelial dysfunction (1); fibrosis (1); frontotemporal dementia (1); gastric cancer (1); Huntington disease (1); hypothyroidism (1); inflammatory bowel disease (1); Insulin resistance (1).
A further 17 diseases each share a sentence with MARK1 in 1 paper.